PPARD (peroxisome proliferator activated receptor delta)
Diseases named in the same sentence as PPARD in open-access papers (continued):
Sharing a sentence is not in itself a finding about the gene and the disease.
atherosclerosis (52 papers, 2007 to 2025). A disease characterized by the build-up of fatty material and calcium deposition in the arterial wall resulting in partial or complete occlusion of the arterial lumen. "PPARD has been clearly clarified to be involved in cholesterol metabolism by encoding the lipid‐activated nuclear receptor and activate gene transcription, and deletion of the gene in ApoE knockout mice showed attenuated atherosclerosis." (PMID 39673281, 2024). "Butyrate inhibits endothelial NOX2 and ROS expression through the PPARδ/miR-181b pathway, thereby improving endothelial function and preventing the development of atherosclerosis." (PMID 40636499, 2025). "Activation of TNFRSF9 signaling on the macrophage surface modulates the STAT6/PPARδ signaling pathway, which induces the polarization of macrophages in atherosclerosis toward the M2 type." (PMID 40599317, 2025). "More evidences indicate the protective roles of PPARδ in blood vessels of cardiovascular disease, and activating PPARδ with agonists or viral vector exerts effects of anti-inflammation, anti-atherosclerosis and anti-oxidation." (PMID 33318871, 2021). "In conclusion, aspirin can systemically and simultaneously ameliorate NAFLD and atherosclerosis by inhibiting lipid biosynthesis and inflammation and by elevating catabolic metabolism through the activation of the PPARδ-AMPK-PGC-1α pathway." (PMID 32258142, 2020). "And the expressions of PPARδ were significantly higher in the process of macrophages differentiation; thus PPARδ has been thought as the target of atherosclerosis therapy." (PMID 31073415, 2019). "Other studies suggest that IL-13 leads to atherosclerosis by inducing expression of peroxisome proliferator activated receptor δ (PPARδ) or PPARβ in the adipose tissue and by increasing CD36 levels." (PMID 30759882, 2019). "The abundant expression of PPARδ in macrophages provided acompelling rationale to study its contribution to macrophagebiology and atherosclerosis." (PMID 17389768, 2007). "Additionally, CD36 has been found to exhibit crosstalk with PPARδ in macrophages, impacting foam cell formation and inflammation in atherosclerosis and in induced inflammation from M. leprae infection models." (PMID 38989454, 2024). "However, further research uncovered its ability to maintain metabolic homeostasis by inducing PPARδ or PPARβ expression in adipose tissue, potentially promoting atherosclerosis." (PMID 37629267, 2023). "Tert-butyl-4-(2-hydroxyethyl)-4-(pyrrolidin-1-yl)-piperidine-1-carboxylate (PYPEP), which is another PPARδ agonist, inhibited atherosclerosis in human apolipoprotein B100 and cholesteryl ester transfer protein double-transgenic mice by improving the serum lipoprotein profiles." (PMID 32258142, 2020). "So PPARδ agonists might become an effective atherosclerosis treatment drug by inhibiting macrophage inflammatory reaction." (PMID 31073415, 2019). "Macrophages played an important role in atherosclerosis, which could mediate inflammatory reaction in the control of PPARδ." (PMID 31073415, 2019). "In mouse models for atherosclerosis, synthetic agonists of PPARδ reduced atherosclerotic lesions." (PMID 28067284, 2017). "PPARδ may serve as a more potent therapeutic target than PPARγ in atherosclerosis or inflammatory therapy, and the potency of 1 μM PPARδ is similar to that of 10 μM PPARγ in anti-inflammatory effect." (PMID 26884762, 2016). "Thus, basal PPARδ activity in macrophagesaugments the pathogenesis of atherosclerosis, and PPARδligands may exert therapeutic effects by reversing, rather thanenhancing, this pathogenic activity." (PMID 17389768, 2007). "Another metabolite, butyrate, can pass through the PPARδ/Mir-181b pathway to reduce NOX2 expression and ROS production in vascular endothelial cells, thereby preventing endothelial dysfunction in atherosclerosis." (PMID 36998018, 2023). "Many studies have reported the effects or roles of PPARδ, AMPK, and PGC-1α on NAFLD and atherosclerosis." (PMID 32258142, 2020).
atherosclerosis (continued). "So the results supposed that aspirin can ameliorate atherosclerosis and NAFLD, and the effects of aspirin are dependent to PPARδ." (PMID 32258142, 2020). "No FDA approved drug targeting PPARδ is available so far notwithstanding early-stage clinical trials on the use of PPARδ agonists (e.g., KD-3010 and MBX-8025) to treat atherosclerosis, metabolic disorders and liver injury." (PMID 31032335, 2018). "In our in vitro study, aspirin normalized the expression of biomarkers related to atherosclerosis and NAFLD in disease-mimicking conditions, and the effects of aspirin may be regulated by the PPARδ-AMPK-PGC-1α pathway." (PMID 32258142, 2020). "Interestingly, several studies have demonstrated that PPARδ agonists such as GW0742 and GW1516 can prevent the progression of atherosclerosis through regulating inflammatory response." (PMID 32314783, 2020).
colorectal cancer (52 papers, 2006 to 2026). A primary or metastatic malignant neoplasm that affects the colon or rectum. "In another study, PPARδ upregulation was associated with reduced metastasis-free survival in various types of cancer, e.g., colorectal cancer." (PMID 39451206, 2024). "PPARδ upregulation is associated with reduced metastasis-free survival in various types of cancer, e.g., colorectal cancer, where PPARδ plays a role in invasion, angiogenesis, and migration." (PMID 39451206, 2024). "Strong evidence supports the role of PPARD in colorectal cancer metastases and was found to be associated with decreased progression-free survival." (PMID 37347737, 2023). "PPARδ is associated with ulcerative colitis (UC) and Crohn's disease (CD), which is involved in the progression of colorectal cancer (CRC)." (PMID 28948004, 2017). "Description of the PPARD variants detected in colorectal cancer patients, healthy controls and cell lines." (PMID 24391853, 2013). "PPARδ plays a pathogenic role in the development of colorectal cancer cells." (PMID 39451206, 2024). "PPARD variant c.489C/C is related to the worse differentiation in colorectal cancer." (PMID 24391853, 2013). "Frequency of recurrent PPARD variants in colorectal cancer patients and healthy controls." (PMID 24391853, 2013). "In a murine model of colorectal cancer, Nanog expression was upregulated in normal and cancerous intestinal cells after PPARδ agonist treatment, and it promoted liver metastasis, but it did not affect the size of the tumor." (PMID 39451206, 2024). "Much attention has been paid to the role of PPARs in oncogenesis, including PPARδ in human endometrial adenocarcinoma and colorectal cancer and PPARγ in gastric or prostate cancer." (PMID 39062500, 2024). "PPARδ knockout or knockdown in CTLs increased their cytotoxicity against colorectal cancer cells, whereas overexpression of PPARδ or agonist treatment decreased it." (PMID 39292167, 2024). "PPARδ is upregulated in human colorectal polyps and colorectal cancers and has been identified as a downstream target of β-catenin." (PMID 31623618, 2019). "Clinical observations show that although PPARδ protein levels are lower in human colon adenocarcinomas, high PPARδ protein levels are benefit of colorectal cancer patients." (PMID 28948004, 2017). "PPARD and PPARB expression is upregulated in colorectal cancer and the gene was found activated by the K-RAS pathways in rat intestinal epithelial cells." (PMID 24875049, 2014). "Coding exons 4 to 9 of the PPARD gene were sequenced in the large human genome analysis of breast and colorectal cancers." (PMID 24391853, 2013). "Peroxisome proliferator-activated receptor delta (PPARD) is nuclear hormone receptor involved in colorectal cancer (CRC) differentiation and progression." (PMID 24391853, 2013). "15-LOX-1 expression alsodownregulated PPARδ expression and transcriptional activityin these colorectal cancer cells." (PMID 18584037, 2008). "The datafrom these two different colorectal cancer models suggest that PPARδ attenuates colon carcinogenesis." (PMID 18528523, 2008). "Colorectal cancer samples expressed various levels of the PPARδ protein that correlated well with those detected by immunohistochemistry." (PMID 16969348, 2006). "Overexpression of PPARD in colorectal cancer leads to enhanced tumor growth and survival." (PMID 39922804, 2025). "PPARδ may play a role in this process, and IBD patients have increased susceptibility to colorectal cancer." (PMID 39451206, 2024). "Furthermore, PPARD agonists have promoted the expression of vascular endothelial growth factor (VGEF) in the colorectal cancer cell lines HT29 and SW480." (PMID 35163565, 2022). "Many studies demonstrated that PPARδ, a ligand-inducible transcription factor, plays a critical role in regulating cancer progression, and PPARδ-related tumorigenesis was first identified in colorectal cancer." (PMID 29416623, 2018).
colorectal cancer (continued). "TCF7L2 could bind to the promoter of PPARD and increase its expression in human colorectal cancer (CRC) cells." (PMID 26599230, 2015). "Moreover,suppression of PPARδ expression by RNAi targeting significantly promoted theproliferation of human colorectal cancer cells (HCT-116) by increasing thenumber of cells in G1 phase." (PMID 19325917, 2009). "Interestingly,the same group also showed that prostaglandin E2 (PGE2),the predominant prostanoid found in most colorectal cancers, indirectlytransactivates PPARδ promoting cell survival and intestinal adenoma formation." (PMID 18528523, 2008). "PPARδ may play a role in the pathogenesis of colorectal cancer’s development." (PMID 39451206, 2024). "Recent studies suggest that PPARδ may play a role in colorectal cancer (CRC)." (PMID 16969348, 2006). "On the other hand, a study performed in primary patient-derived colorectal cancer cells demonstrated that an acidic TME promoted stemness and chemoresistance by downregulating PPARD expression in colorectal CSCs." (PMID 41148824, 2025). "Recently, a study showed that PPAR expressions are explicitly deregulated in colorectal cancer (CRC), with PPARα and PPARδ being overexpressed, while PPARγ is suppressed in CRC tumor tissues." (PMID 35481240, 2022). "Treatment with the PPARδ agonist GW0742, through the targeting of the METRNL-E2F-PPARδ pathway, reduces the maximal respiratory capacity of METRNL, thereby inhibiting the growth of orthotopic gliomas in mice, as well as flank prostate and colorectal cancer." (PMID 40155378, 2025). "Interestingly, both PPARD and TGF-beta signaling share a common target, Angiopoetin-like 4, known to be involved in colorectal cancer metastasis." (PMID 37347737, 2023). "PPARδ activity is also involved ina negative control of colorectal cancer and keratinocyte cell apoptosis." (PMID 19325917, 2009). "Sulindac sulfideand indomethacin inhibit both 14-3-3 proteins and PPARδ levels in HT29 cells,suggesting that this could be the mechanism by which NSAIDs induce apoptosisin colorectal cancer." (PMID 18528523, 2008).
type 2 diabetes (47 papers, 2007 to 2026). "The effects of PPARD variants on type 2 diabetes and the metabolic related traits has been widely investigated, however, the results were inconsistent." (PMID 22509365, 2012). "We investigated the associations of variants in PPARD with the risks of type 2 diabetes in a Chinese Han population by case-control analyses." (PMID 22509365, 2012). "Our findings demonstrate that common variants in PPARD contribute to the risk of type 2 diabetes in Chinese Hans, and provided suggestive evidence of interaction between 25(OH)D levels and PPARD-rs6902123 on HbA1c." (PMID 22509365, 2012). "Associations of rs6902123 in PPARD with type 2 diabetes and combined phenotype of type 2 diabetes and impaired fasting glucose in Chinese Hans." (PMID 22509365, 2012). "In conclusion, we have reported for the first time that PPARD-rs6902123 C allele was associated with higher fasting glucose, HbA1c, and increased risk of type 2 diabetes and combined IFG/type 2 diabetes in a population-based Chinese Han sample." (PMID 22509365, 2012). "The underlying mechanisms responsible for the association between PPARD-rs6902123 and type 2 diabetes remain to be elucidated." (PMID 22509365, 2012). "In order to completely understand the role of PPARD in etiology of type 2 diabetes, investigation on the interactions between environmental factors and common genetic variants in PPARD is required." (PMID 22509365, 2012). "Among the 9 PPARD tag SNPs, rs6902123 was significantly associated with risk of type 2 diabetes (odds ratio 1.75 [95%CI 1.22–2.53]; P = 0.0025) and combined type 2 diabetes and impaired fasting glucose (IFG) (odds ratio 1.47 [95%CI 1.12–1.92]; P = 0.0054)." (PMID 22509365, 2012). "In rosiglitazone-treated obese patients with type 2 diabetes, improved insulin sensitivity and skeletal muscle oxidative enzyme activity is associated with an upregulation of PPARδ expression." (PMID 22190906, 2011). "This suggests that the PPARD-87C>T polymorphism might be a factor that affects the progression of type 2 diabetes." (PMID 25132859, 2014). "Therefore, the primary aim of this study is to investigate the effect of PPARD SNPs on the risk of having type 2 diabetes and its related phenotype in a relative large population-based Han Chinese sample." (PMID 22509365, 2012). "Hence, Vitamin D status might influence the effect of variants in PPARD on risk of type 2 diabetes and related traits." (PMID 22509365, 2012). "We have previously shown that pro-angiogenesis activity of DHI coordinately activated VEGF/VEGFR-2 and PPARδ pathways and accelerated recovery from peripheral arterial disease in type 2 diabetic mice." (PMID 34983572, 2022). "In obese patients with type 2 diabetes, rosiglitazone increased insulin sensitization through upregulation of mRNA levels of PPARδ and PGC-1α, as well as stimulation of SDH activity in skeletal muscles." (PMID 29201040, 2017). "Activation of PPARD has beneficial effect on body weight and is proposed as treatment of type 2 diabetes." (PMID 24799886, 2014). "The PPARD-rs6902123 C allele exhibited significant associations with increased risk of type 2 diabetes, combined IFG/type 2 diabetes, higher fasting glucose and HbA1c." (PMID 22509365, 2012). "A range of complementary metabolic profiling approaches were used to study key tissues involved in type 2 diabetes from ob/ob mice treated with a PPARδ or a PPARγ agonist to understand the role of PPAR-δ in regulating systemic metabolism." (PMID 19968882, 2009). "PPARδ is the less studied receptor of this group while PPARα and PPARγ have been extensively investigated as therapeutic targets especially in metabolic diseases like type 2 diabetes (T2D)." (PMID 36176461, 2022). "In subjects with and without type 2 diabetes, PPARD +294T>C was associated with BMI, HDL-C, leptin, and TNF-alpha and was dependent on gender." (PMID 23039238, 2012).
type 2 diabetes (continued). "Our work might lead to a better understanding of the role of PPARδ as a potential therapeutic target in treating hyperlipidemia and type 2 diabetes." (PMID 22792088, 2012). "Among subjects with and without type 2 diabetes, the PPARD +294T > C polymorphism was associated with HDL-C and was dependent on sex." (PMID 21176135, 2010). "Previous candidate gene association studies in Europeans have reported that common variants in PPARD were associated with fasting glucose, insulin resistance, BMI, LDL-cholesterol, HDL-cholesterol,and risk of conversion from impaired glucose tolerance (IGT) to type 2 diabetes." (PMID 22509365, 2012). "However, no further association with type 2 diabetes or combined IFG/type 2 diabetes were detected for the rest PPARD variants in our study." (PMID 22509365, 2012). "Next, an exploratory study was conducted to assess the interactive effects of PPARD-rs6902123 and 25(OH)D levels on type 2 diabetes, combined IFG/type 2 diabetes, and their related traits." (PMID 22509365, 2012). "For PPARD-rs2016520 variant, we only found a marginal association with combined IFG/type 2 diabetes, but not with the risk of type 2 diabetes and related traits." (PMID 22509365, 2012). "The PPARD +294T > C polymorphism was associated with HDL-C and was dependent on sex among subjects with and without type 2 diabetes." (PMID 22192471, 2011).